FITM2 (fat storage inducing transmembrane protein 2)
Description:
Fatty acyl-coenzyme A (CoA) diphosphatase that hydrolyzes fatty acyl-CoA to yield acyl-4'-phosphopantetheine and adenosine 3',5'-bisphosphate (By similarity). Preferentially hydrolyzes unsaturated long-chain acyl-CoA substrates such as oleoyl-CoA/(9Z)-octadecenoyl-CoA and arachidonoyl-CoA/(5Z,8Z,11Z,14Z)- eicosatetraenoyl-CoA in the endoplasmic reticulum (ER) lumen (By similarity). This catalytic activity is required for maintaining ER structure and for lipid droplets (LDs) biogenesis, which are lipid storage organelles involved in maintaining lipid and energy homeostasis (By similarity). Directly binds to diacylglycerol (DAGs) and triacylglycerol, which is also important for LD biogenesis (By similarity). May support directional budding of nacent LDs from the ER into the cytosol by reducing DAG levels at sites of LD formation (By similarity). Plays a role in the regulation of cell morphology and cytoskeletal organization.
Synonyms: C20orf142; FIT2; dJ881L22.2; SIDDIS
Tractability: Antibody: UniProt predicts a signal peptide or a membrane-spanning region. PROTAC: its protein half-life has been measured.
Gene: Protein-coding gene on chromosome 20 (44,302,840 to 44,311,202, reverse strand). Ensembl gene ENSG00000197296.
Subcellular location: Endoplasmic reticulum membrane
Pathways (Reactome):
Metabolism: Lipid particle organization
Gene Ontology:
Molecular function: coenzyme A diphosphatase activity; protein binding; diacylglycerol binding; endoplasmic reticulum-lipid droplet tether activity; triglyceride binding
Biological process: fatty-acyl-CoA catabolic process; lipid droplet formation; lipid homeostasis; fat cell differentiation; intracellular triglyceride homeostasis; lipid droplet organization; lipid storage; phospholipid biosynthetic process; triglyceride metabolic process
Cellular component: endoplasmic reticulum membrane
Genetic constraint (gnomAD): Loss-of-function variants: 16 observed, 24.57 expected, observed/expected ratio (o/e) 0.65, 90% interval 0.44 to 0.99. The upper end of that interval is the gene's LOEUF score, 0.99, which puts it in group 4 of 6, group 1 being the genes least tolerant of losing a copy. Missense variants: 273 observed, 344.67 expected, observed/expected ratio (o/e) 0.79, 90% interval 0.72 to 0.88. Synonymous variants: 132 observed, 148.96 expected, observed/expected ratio (o/e) 0.89, 90% interval 0.77 to 1.02.
Gene-disease validity (ClinGen):
ClinGen rates the evidence that FITM2 causes each of these diseases.
Siddiqi syndrome (autosomal recessive): Definitive. An autosomal recessive disorder characterized by early-onset progressive sensorineural hearing impairment, global developmental delay, regression of motor skills, dystonia, and low body mass index.
Homologues: Orthologues: chimpanzee FITM2 (100% identical), macaque FITM2 (99% identical), dog FITM2 (92% identical), guinea pig FITM2 (88% identical), mouse Fitm2 (87% identical), rat Fitm2 (87% identical), rabbit FITM2 (83% identical), pig FITM2 (76% identical), tropical clawed frog fitm2 (57% identical), zebrafish fitm2 (44% identical), Drosophila melanogaster Fitm (29% identical), Caenorhabditis elegans fitm-2 (25% identical). Paralogues in human: FITM1 (30% identical).
Diseases named in the same sentence as FITM2 in open-access papers:
FITM2 is named in the same sentence as 31 diseases in open-access papers, as found by Europe PMC text mining. Sharing a sentence is not in itself a finding about the gene and the disease. The quoted sentences say what the papers report.
deafness (3 papers, 2017 to 2023). An inherited or acquired condition characterized by the complete loss of the ability to hear from one or both ears. "In humans, homozygous FITM2 deficiency causes deafness–dystonia syndrome, and human FIT2 is required for cancer cell fitness during exposure to interferon γ (IFNγ)." (PMID 36805337, 2023). "Testing mitochondrial fatty acid oxidation was compelling as the deafness–dystonia syndrome reported in humans with FITM2 mutations is reminiscent of a similar disorder, Mohr-Tranebjaerg syndrome, that is caused by defects in mitochondrial function." (PMID 36805337, 2023). "We report the second known family affected by deafness-dystonia syndrome associated with loss of function of FITM2." (PMID 30214770, 2018).
deafness dystonia syndrome (3 papers, 2017 to 2023). An X-linked recessive neurodegenerative syndrome characterized by clinical manifestations commencing with early childhood onset hearing loss, followed by adolescent onset progressive dystonia or ataxia, visual impairment from early adulthood onwards and dementia from the 4th decade onwards. "In conclusion, we have described a novel deafness-dystonia syndrome that is causally related to a loss-of-function mutation in FITM2, the phenotypic effects of which are recapitulated in a Drosophila model." (PMID 28067622, 2017).
diabetes (3 papers, 2018 to 2024). "SFAs reduce fat storage-inducing transmembrane protein 2 (FIT2) which leads to β cell dysfunction and death, leading to diabetes." (PMID 39183283, 2024). "Here, we show how saturated fatty acids (SFAs) reduce fat storage–inducing transmembrane protein 2 (FIT2)–facilitated, pancreatic β cell LD biogenesis, which in turn induces β cell dysfunction and death, leading to diabetes." (PMID 35254894, 2022).
Siddiqi syndrome (3 papers, 2017 to 2026). "We report the first two Iranian siblings with Siddiqi syndrome, carrying a novel likely pathogenic FITM2 variant." (PMID 41113320, 2025).
Dystonia (2 papers, 2021 to 2023). An abnormally increased muscular tone that causes fixed abnormal postures. "In humans, a homozygous nonsense mutation in FITM2 was identified in a family with Siddiqi syndrome, characterized by deafness–dystonia syndrome, delayed development, and regression of motor skills, dystonia, ichthyosis-like features, signs of sensory neuropathy, and low body mass index." (PMID 33898445, 2021).
enteropathy (2 papers, 2017 to 2019). "FITM2 causes lethal enteropathy and plays an essential role in regulating intestinal health." (PMID 31073530, 2019).
lipodystrophy (2 papers, 2017 to 2024). A congenital or acquired disorder characterized by abnormal loss or redistribution of the adipose tissue in the body. "Furthermore, mutations in FIT2 (Fat storage-inducing transmembrane protein 2, an ER membrane protein critical for lipid droplet biosynthesis) may be associated with lipodystrophy." (PMID 38706718, 2024). "Editors' choice: Loss of FITM2 function in humans causes syndromic hearing loss without any signs of a lipodystrophy, although FITM2 is known to function in lipid droplet synthesis and metabolism." (PMID 28067622, 2017). "Despite the role of FITM2 in neutral lipid storage and metabolism, no indications for lipodystrophy were observed in the affected individuals." (PMID 28067622, 2017).
type 2 diabetes (2 papers, 2015 to 2022). "In a three-stage association study performed with an east Asian population FITM2 was shown to associate with type 2 diabetes." (PMID 26232096, 2015).
atherosclerosis (1 paper, 2024). A disease characterized by the build-up of fatty material and calcium deposition in the arterial wall resulting in partial or complete occlusion of the arterial lumen. "On the other hand, our study shows that the Pep_A6 vaccine can regulate the expression of liver genes such as Fitm2, Gk, Plin2, Acsl1, Fatp1, and Acot4, thereby lowering serum LDL-C levels and hepatic lipid accumulation while improving atherosclerosis." (PMID 39329770, 2024).
chronic heart failure (1 paper, 2019). "The mRNA expression of Fitm1 and Fitm2 was decreased in heart failure model mice, and Fitm2 hetero-knockout [Fitm2 (+/−)] mice exhibited resistant profiles to pressure-induced chronic heart failure." (PMID 30923760, 2019).
cognitive decline (1 paper, 2025). "In animal models, targeting the Fat Storage-Inducing Transmembrane Protein 2 (FIT2) protein to reduce lipid droplet accumulation in microglia has been shown to indirectly enhance oligodendrocyte function and mitigate cognitive decline." (PMID 40761314, 2025).
colon cancer (1 paper, 2022). "In our study, FITM2 was highly expressed in colon cancer tissues." (PMID 35991564, 2022). "ALPL, APOL6, SON, VWF, FITM2, and ZEB1-AS1 were significantly differentially expressed in normal and colon cancer tissues." (PMID 35991564, 2022).
glioblastoma (1 paper, 2021). The most malignant astrocytic tumor (WHO grade IV). "For other activities, puerarin downregulated cytochrome c oxidase 19 (Cox19), fat storage-inducing transmembrane protein 2 (Fitm2), and glioblastoma amplified sequence (Gbas)." (PMID 34707778, 2021).
heart failure (1 paper, 2019). Inability of the heart to pump blood at an adequate rate to meet tissue metabolic requirements. "Our findings collectively suggest that downregulation of Fitm, especially Fitm2 expression or function may have a beneficial effect in patients with heart failure." (PMID 30923760, 2019). "Therefore, we here report the profiles of FITM1 and FITM2 in mouse models of heart failure." (PMID 30923760, 2019).
hepatocellular carcinoma (1 paper, 2023). A malignant tumor that arises from hepatocytes. "Additionally, high intratumoral levels of FITM2 expression correlate with decreased survival in human patients with hepatocellular carcinoma." (PMID 36805337, 2023).
leukemia (1 paper, 2023). A malignant (clonal) hematologic disorder, involving hematopoietic stem cells and characterized by the presence of primitive or atypical myeloid or lymphoid cells in the bone marrow and the blood. "To determine whether Fitm2 loss similarly sensitizes our leukemia cells to IFNγ, we generated Fitm2 KO cells and treated them with IFNγ in vivo and in vitro." (PMID 38052854, 2023).
Sensory neuropathy (1 paper, 2017). Peripheral neuropathy affecting the sensory nerves. "As signs of a sensory neuropathy are part of the syndrome caused by a nonsense mutation in FITM2, we evaluated the role of Fitm in sensory neuron development by inspecting the dorsal class IV dendritic arborization C (ddaC) neurons in third instar larvae." (PMID 28067622, 2017).
tumor (3 papers, 2020 to 2023). "Like Ptpn2, Fitm2 loss has previously been shown to sensitize tumor cells to T cell-mediated killing." (PMID 38052854, 2023). "Interestingly, the authors uncovered that loss of autophagy genes in the context of Fitm2 loss resulted in resistance to IFN-γ, highlighting the importance of genetic interactions in tumor cell-CTL evasion." (PMID 33277468, 2020). "The authors then focus on the lipid-droplet-related gene, Fitm2, which scored as the top hit but has not previously been associated with tumor sensitivity to IFN-γ." (PMID 33277468, 2020). "In contrast, FITM2 and ZEB1-AS1 were highly expressed in tumor tissues." (PMID 35991564, 2022).
metabolic disease (2 papers, 2018 to 2024). A congenital disorder (due to inherited enzyme abnormality) or acquired (due to failure of a metabolically important organ) disorder resulting from an abnormal metabolic process. "Impairment of FITM2 function is linked with metabolic disorders such as type-2 diabetes, insulin resistance, lipodystrophy, and non-metabolic diseases such as deafness-dystonia syndrome." (PMID 39421023, 2024).
infection (1 paper, 2022). The state of being infected such as from the introduction of a foreign agent such as serum, vaccine, antigenic substance or organism. "Other genes, such as FITM2, reportedly restrict the entry of COVID-19 virus into cells, but its expression in CD8+ Effector T cells and its dynamic characteristics at different stages of infection have not been studied." (PMID 36437952, 2022).
FITM2 also shares sentences with these, for which no sentence is quoted: cancer (1 paper); cardiomyopathy (1); colon adenocarcinoma (1); Hearing impairment (1); hearing loss (1); Hyperinsulinemia (1); ichthyosis (1); liver steatosis (1); Obesity (1); small fiber neuropathy (1); steatosis (1).